SOX3 (SRY-box transcription factor 3)
Diseases named in the same sentence as SOX3 in open-access papers (continued):
Sharing a sentence is not in itself a finding about the gene and the disease.
tumor (continued). "Expanding our understanding of the regulatory mechanisms of SOX3 was a series of in silico experiments and functional assays, revealing that miR-483 and miR-483-3p target SOX3, impacting its expression and thereby affecting tumor cell behavior." (PMID 38927713, 2024). "SOX3 was overexpressed in 42 cases of human OS tissues in comparison with non-tumor samples." (PMID 38927713, 2024). "In addition, 72 h MEKi altered genes associated with germ cell or other tumours, or SSC function including higher Dmrt1 and Sox3 and lower Rhox10 expression." (PMID 38053127, 2023). "SOX3 expression was increased in most OS samples relative to non-tumor samples." (PMID 28335789, 2017). "Sox3 followed the same expression pattern as Sox2 in all tumor samples examined." (PMID 21483788, 2011). "We show that Sox3-Snail antagonism is implemented through direct reciprocal transcriptional repression, a relationship that seems to be conserved in the mouse embryo and in tumor cell lines, where they also regulate epithelial versus mesenchymal and invasive properties." (PMID 21920318, 2011). "Because Snail factors are also implicated in the repression of the epithelial phenotype and the induction of EMT during tumor progression, we checked whether human cancer cell lines also show an antagonistic relationship between Snail and Sox3 transcription factors." (PMID 21920318, 2011). "Furthermore, artificial intelligence-driven clustering of SOX expression with tumor mutational burden (TMB) and immune signatures may help identify resistance patterns or novel biomarkers, while bioinformatics analysis of SOX3 methylation may demonstrate diagnostic value." (PMID 41268614, 2026). "This regulation represses genes like SOX3, which oppose the mitotic and OLIG2-positive tumor phenotype." (PMID 40565099, 2025). "The findings revealed a significant upregulation of SOX3 mRNA and protein expression in HCC tissues compared to adjacent non-tumor regions." (PMID 38927713, 2024). "Through this mode of action, CELF2 can repress genes such as SOX3, which we have shown to oppose the phenotype of mitotic/OLIG2-positive tumor cells." (PMID 37894405, 2023). "We next detected SOX3 location in tumour tissues using immunofluorescence and ascertained that SOX3 was expressed in tumour parenchyma rather than tumour stroma." (PMID 32363730, 2020). "Among the SOX family proteins studied, the SOX3 protein plays a role in the regulation of cell proliferation in oral melanomas, and it is suggested that the SOX2 and SOX10 proteins are constitutively expressed in these neoplasms, without a determining role for aggressiveness." (PMID 41012776, 2025).
cancer (11 papers, 2011 to 2025). A tumor composed of atypical neoplastic, often pleomorphic cells that invade other tissues. "These works illustrate a shared pathway in different types of cancer cells where SOX3 suppression leads to increased apoptosis." (PMID 38927713, 2024). "This enables SOX3 to participate in complex signaling networks that regulate cancer progression, including pathways involving AKT, NF-κB, and MYC." (PMID 38927713, 2024). "SOX3 and other SOX protein activities are known to be modulated by post-translational modifications (PTMs) such as sumoylation, acetylation and phosphorylation, which significantly impact SOX3 function and role in cancer progression." (PMID 38927713, 2024). "The complexity uncovered in SOX3 function emphasizes the need for further research to unravel its full potential in cancer therapeutics." (PMID 38927713, 2024). "This discrepancy, again, highlights the context-dependent nature of SOX3 influence on cell proliferation, suggesting that its impact varies across different cancer types." (PMID 38927713, 2024). "This duality in SOX3 function emphasizes the complexity of gene regulation within cancer biology, where SOX3 interactions are pivotal and exceedingly context-dependent." (PMID 38927713, 2024). "Our review seeks to uncover the multifaceted role of SOX3 in cancer progression, potentially opening new avenues for understanding and targeting this TF in cancer therapeutics." (PMID 38927713, 2024). "We compared the expression levels (mRNA) of SOX B1 family members (SOX1, SOX2 and SOX3) in various cancers and normal tissue using the ONCOMINE database." (PMID 34953010, 2022). "The transcription factor sex-determining region Y-box protein 3 (SOX3) plays important roles in various types of cancer." (PMID 28335789, 2017). "SOX3 was increased in epithelial ovarian cancer, and promoted proliferation, migration and invasion and inhibited apoptosis of cancer cells." (PMID 29132362, 2017). "In summary, the antagonistic relationship between Snail1 and Sox3 is maintained in cancer cells, and their relative expression correlates with their morphological, motility and invasive properties." (PMID 21920318, 2011). "We also show that the relationship between Sox3 and Snail is conserved in the mouse embryo and in human cancer cells." (PMID 21920318, 2011). "These tumorspheres serve as a cancer stem cell model indicative of SOX3 as an ECSC marker." (PMID 38927713, 2024). "However, limited attention has been devoted to another SOX B1 group member, SOX3, leaving its role in cancer relatively unexplored." (PMID 38927713, 2024). "Collectively, our research suggested that SOX2 might serve as a cancer‐promoting gene to identify high‐risk GBM patients, and SOX3 had the potential to be a prognostic biomarker for GBM patients." (PMID 34953010, 2022). "There were seldom studies regarding the roles of SOX3 in cancer." (PMID 32363730, 2020). "This hypothesis is also supported by the fact that p63 and Sox2, which is functionally very similar to Sox3, bind a subset of common BSs and physically interact in cancer cells." (PMID 31296872, 2019). "Finally, our data obtained in human cancer cell lines suggest that the mutual repression between Sox3 and Snail is also in place." (PMID 21920318, 2011). "Consequently, SOX3 emerges as a promising prognostic factor in GC patients, showing potential oncogenic properties and positioning itself as a candidate for targeted intervention aimed at suppressing cancer progression." (PMID 38927713, 2024). "Together, our results show that Snail-Sox3 cross-repression regulates cell ingression at gastrulation in amniotes and suggest that this antagonistic relationship may also have important implications in cancer." (PMID 21920318, 2011). "The correlation with metastasis is proposed to be influenced by SOX3 positive modulation of matrix metalloproteinase-9 (MMP-9), a key player in cancer cell migration." (PMID 38927713, 2024).
cancer (continued). "By comparing the transcription levels of SOX B1 in pan‐cancer through ONCOMINE and GEPIA data sets, SOX2 was overexpressed in GBM and LGG and SOX3 had elevated expression in LGG." (PMID 34953010, 2022).
bone cysts (1 paper, 2017). "SOX3 was overexpressed in most OS tissues compared with that in bone cysts." (PMID 28335789, 2017). "Next, the SOX3 mRNA level was assessed in OS tissues and bone cysts." (PMID 28335789, 2017).
infection (1 paper, 2025). The state of being infected such as from the introduction of a foreign agent such as serum, vaccine, antigenic substance or organism. "In support of this idea, RNA-Seq and RT-qPCR analysis revealed that the expression of Sox3,but not Sox1, increased immediately after lenti-Cre infection of Sox2F/F ESCs and reached a peak around day 9 and then remained at that level thereafter." (PMID 40216251, 2025).
SOX3 also shares sentences with these, for which no sentence is quoted: hypoparathyroidism (5 papers); Cognitive impairment (2); holoprosencephaly (2); scoliosis (2); acute myeloid leukemia (1); Anophthalmia (1); Anxiety (1); Azoospermia (1); Bardet-Biedl syndrome (1); brain disease (1); cat-eye syndrome (1); central nervous system tuberculosis (1); choriocarcinoma (1); coloboma (1); cortical dysplasia (1); craniopharyngioma (1); cryptorchidism (1); Dent disease (1); dental disorder (1); developmental delay (1); Disorders of Sex Development (1); dysplasia (1); endocrine disorder (1); endocrine tumor (1); endometrial carcinoma (1); epilepsy (1); Esophageal atresia (1); FRAXE syndrome (1); gastric adenocarcinoma (1); genetic disorder (1).
A further 29 diseases each share a sentence with SOX3 in 1 paper.